TNF (tumor necrosis factor)
Diseases named in the same sentence as TNF in open-access papers (continued):
Sharing a sentence is not in itself a finding about the gene and the disease.
kidney (146 papers, 2006 to 2026). "In vivo studies using Ripk3- or Mlkl-deficient mice validated kidney ischemia reperfusion injury and high-dose tumor necrosis factor (TNF) availability, as druggable targets in necroptotic-mediated pathologies." (PMID 30842945, 2019). "In the process of kidney injury, M1 macrophages promote inflammation and tubular cell apoptosis by secreting pathogenic factors such as IL-1β, TNF-α and IL-6; however, M2 macrophages reduce inflammation and promote renal recovery by secreting trophic factors such as IL-10, TGF-β and arginase-1." (PMID 38785317, 2024). "The cytokine theory is a mainstream theory in the research of radiation lung injury; it is also a hot spot of current research, and the cytokines that cause radiation lung injury mainly include tumor necrosis factor-α (TNF − α), interleukin-6 (IL-6), transforming growth factor (TGF − β1), and so on." (PMID 35002569, 2021). "We compared markers of kidney inflammation and injury (neutrophil gelatinase-associated lipocalin, kidney injury molecule-1) as well as plasma and urine levels of T cell-associated cytokines (TNF-α, interferon-γ, interleukin (IL)-2, IL-4, IL-6, IL-8, IL-9, and IL-10) between groups." (PMID 36938084, 2023). "The levels of IL-1β, IL-6, and TNF-α were measured to investigate the impact of SP nutritional intervention on liver inflammation in ALD mice." (PMID 40362898, 2025). "We previously identified differentially expressed genes involved in apoptosis and TNF-α signaling in proximal tubular cells from mice with kidney IR injury treated with miR-486-5p." (PMID 38739452, 2024). "Previous studies found that the activation of the PI3K/Akt signaling pathway during liver ischemia-reperfusion injury, increased IL-4, and IL-10 expressions, decreased IL-1β and TNF-α expressions, and reduced the hepatic inflammatory response." (PMID 36835571, 2023). "The present findings showed that RC significantly inhibited the levels of MCP-1, TNF-α, and IL-6, thereby decreasing the level of liver inflammation in NAFLD." (PMID 36660274, 2023). "When tubular epithelial cells were stimulated with several inflammatory cytokines, including TNF‐α, interleukin (IL)-1β, and IL-6, EMT was facilitated in the development of allograft kidney IF; however, the underlying mechanisms remained ambiguous." (PMID 37507403, 2023). "Oolong tea down regulated IL-6 and up regulated the expression of IL-10 to alleviate alcoholic liver injury, while white tea down regulated TNF-α and IL-6 and up regulated IL-10." (PMID 35677547, 2022). "TNF-α, one of the pro-inflammatory cytokines commonly upregulated in acute lung injury, triggers CRS and facilitates SARS-CoV-2 interaction with angiotensin-converting enzyme 2 (ACE2)." (PMID 35223745, 2022). "A Chinese formula, RDN, had been proved to ameliorate LPS-induced acute lung injury by downregulating TNF-α." (PMID 34938184, 2021). "In brief, kidney damage triggers the release of tumor necrosis factor-α (TNF-α), interleukin (IL)-1β, IL-6, and IL-8, which stimulate prolonged activation of inflammatory cells." (PMID 34769064, 2021). "Markers of kidney inflammation, such as TNFα, IL1β, IL10, F4/80, MCP-1, and CRP, were assessed in total kidney tissues, isolated from both APN-KO and control mice." (PMID 33904399, 2021). "Here we got similar results as a recent study that hippocampal and serum levels of TNF-α, IL-1β, IL-6 were elevated accompanied by a drop in IL-10 level 24 h after middle cerebral artery occlusion in rats." (PMID 32848589, 2020). "Effects of liver IR combined with intraperitoneal administration of aucubin (1, 5, and 10 mg/kg for 10 days) on serum TNF-α, IL-1β, and HMGB1 levels in experimental rats." (PMID 33013386, 2020). "Macrophages isolated from liver granulomas produce TNF-α, and TNF-α anti-serum shrinks liver granulomas in mice." (PMID 31515495, 2019).
kidney (continued). "It is possible that JNK and TNF-α commonly contribute to kidney damage by assembling a positive feedback cycle after CS, leading to increased apoptosis in the renal cortex." (PMID 28701229, 2017). "Compared with the control and sham operation groups, TNF-α concentrations were significantly increased in plasma from rats with liver IR." (PMID 24898700, 2014). "In a lipopolysaccharide-induced acute lung injury model, dexmedetomidine improved congestion and edema and reduced the w/d weight ratio and TNF-α, IL-1β and IL-6 levels in lung tissues." (PMID 24345905, 2014). "This choice was made upon many in vivo and in vitro observations designating both IFN-γ and TNF-α as key regulator cytokines during kidney transplant rejection." (PMID 23717673, 2013). "The results obtained from in vivo study suggested that RPE mitigated alcoholic liver injury and hepatic lipid deposition induced by Lieber-DeCarli diet in rats as well as TNF-α release, protein expression of endotoxin receptors, and KCs activation in liver." (PMID 23133491, 2012). "In a left coronary artery ligation-induced I/R injury model, oral administration of quercetin at 2, 10, or 20 mg/kg for five consecutive days significantly reduced serum and myocardial levels of TNF-α, IL-6, and IL-1β." (PMID 40672380, 2025). "Pre-treatment with the investigated compounds prevented an L-arginine-induced increase in serum and tissue kidney damage markers and, additionally, decreased the levels of inflammation-related parameters (TNF-α and nitric oxide concentrations and myeloperoxidase activity)." (PMID 38256015, 2024). "In addition, the levels of tumour necrosis factor (TNF)-α, and interleukin (IL)-6 were measured to assess inflammation and was estimated kidney oedema." (PMID 37378741, 2023). "FGF10 is known to protect neurons against oxygen-glucose deprivation injury in vitro, and FGF10 treatment depressed the triggered inflammatory factors of the TNF-α, IL-6, and nuclear factor-κB signaling pathways in a mouse middle cerebral artery occlusion model." (PMID 34383782, 2021). "The results showed that the content of propionic acid was negatively correlated with liver lipid accumulation (hepatic TG) and liver inflammation indexes (TNF-α, IL-1β and IL-6), while the content of butyric acid was negatively correlated with liver inflammation." (PMID 35052765, 2021). "Moreover, MF reduced the expression patterns of pro-inflammatory cytokines tumor necrosis factor alpha (TNF-α) and interleukin (IL)-1β, thus ameliorating acute lung injury induced by lipopolysaccharide." (PMID 33414721, 2020). "Additionally, mTOR-deficient mice showed greater expression levels of inflammation-related genes such as MCP-1, TNF-α, and IL-6 than wild-type (WT) mice after liver IR via negatively modulating NF-κB." (PMID 31827701, 2019). "TNF-α was also reported significantly promoting the process of EMT in colorectal cancer." (PMID 29238068, 2017). "Based on the results presented here, stimulation of glycolysis and growth factor production are two mechanisms by which TNFα and IL-17 might cooperate in promoting colorectal carcinogenesis." (PMID 23866118, 2013). "Chronic liver injury and repair ensuing CCl4 exposure release a large amount of inflammatory mediators from HSCs e.g. nuclear factor kappa-light-chain-enhancer of activated B cells (NF-κB), tumor necrosis factor alpha (TNF-α) and transforming growth factor (TGF-β) 7–9." (PMID 41535693, 2026). "Besides, a study revealed that the protective mechanism of Ficus hirta Vahl against alcoholic liver injury involves decreasing the levels of inflammatory factors such as NF-κB, tumor necrosis factor (TNF)-α, IL-1β, and IL-6 while increasing the levels of GSH and SOD." (PMID 40385474, 2025).
kidney (continued). "Nevertheless, there are also studies indicating that Mlkl deficiency confers less protection in the kidney IRI model compared to Ripk3 deficiency, and in contrast to Ripk3-deficient mice, Mlkl-deficient mice resemble wild-type mice in their sensitivity to hypothermia induced by low-dose TNF." (PMID 30842945, 2019). "Cytokines such as interleukin (IL)-6, tumor necrosis factor (TNF)-α, and transforming growth factor (TGF)-β1 in the kidney were assessed as a measures of kidney inflammation." (PMID 34940691, 2021). "Upon analysis, expression of the cytokines IFNB1, IFNG (IFN-γ), TNF (TNF-α), TGFB1 (TGF-β), IL1B, IL2, IL6, CXCL8 (IL-8), and IL10 were all significantly increased in ‘mesenchymal’ lung ADC compared to ‘epithelial’ tumors." (PMID 29440769, 2018). "Lipopolysaccharide‐induced kidney dysfunction via NF‐κB and MAPK activation, by excessive production of IL‐6, TNF‐α, iNOS, and COX‐2, producing perturbance in energy metabolism and oxidative stress." (PMID 28174688, 2017). "In the present study, we have shown that inflammation molecules such as IL-6, TNF-α, MCP-1 and MIP-2 are elevated in IRI kidney." (PMID 28842716, 2017). "There is no doubt that TNF-α can promote fibrosis and lead to chronic liver injury and inflammation." (PMID 33808318, 2021). "The induction of liver IR injury did not affect the tissue concentrations of IL-6 and TNF, however, a significant decrease in the tissue concentration of these cytokines was observed in the HGIR group, compared with both IR and SH groups." (PMID 34824916, 2021). "IL-18 is a proinflammatory cytokine (known as IFN-γ inducing factor), increased the levels of circulating inflammatory cytokines such as TNF-α and IFN-γ in the presence of stimuli and resulted in a worsening of the acute kidney injury, and further damage to renal function." (PMID 32824088, 2020). "Similarly, activation of mTORC1 induced by PTEN deficiency promotes the M2 polarization of macrophages and increases the production of IL-10, decreasing the release of TNF-α, IL-6, and IL-12 when responding to TLR stimulation in liver IR injury." (PMID 31827701, 2019). "The importance of tumor necrosis factor alpha (TNF-α), interferon gamma (INF-γ), and chemoattractant protein-1 macrophage (equivalent to human IL-8) in the early phase of graft reperfusion was shown in a rat lung IR model." (PMID 26161240, 2015). "Even though the absolute number of monocytes was decreased after Tx, the percentage of TNF-α and IFN-γ producing monocytes was significantly increased in kidney transplant recipients at the time of Tx and at 3 months post-transplant compared to healthy controls." (PMID 23922945, 2013). "Evidence has revealed that the absence of TLR4 genes in the liver reduces liver IR injury, and TLR4 blockade affects the function of hepatocytes and Kupffer cells, depresses the production of proinflammatory cytokines (TNF-α and IL-6) and ameliorates hepatocellular IR injury." (PMID 27347929, 2016).
psychiatric disorder (118 papers, 2008 to 2026). A disorder characterized by behavioral and/or psychological abnormalities, often accompanied by physical symptoms. "The activation of inflammatory cytokines such as interleukin-6 (IL-6) and tumor necrosis factor-alpha (TNF-α) has been implicated in both mental illnesses and metabolic disturbances." (PMID 40376339, 2025). "In the present study, we initially examined the effects of NS on IL-6 and TNF-α levels, owing to the strong association between these cytokines and mental illness." (PMID 38339101, 2024). "Several inflammation cytokines, such as TNF and IL-6 in serum, have been considered as sensitive biomarkers in identifying a predisposition for psychiatric disorder or as a diagnosis of a psychiatric disorder." (PMID 34394017, 2021). "Changes of the tumor necrosis factor-alpha (TNF-α) system have been shown to be involved in the development of psychiatric disorders and are additionally associated with changes in body weight as well as endocrine and metabolic changes in psychiatric patients." (PMID 19506720, 2008). "As demonstrated by several animal and clinical studies, TNF-α leads to neuronal damage and is associated with several psychiatric disorders, such as Alzheimer’s disease, Parkinson’s disease, autism spectrum disorder, MDD, schizophrenia, and posttraumatic stress disorder." (PMID 36835209, 2023). "Moreover, specific probiotics have been found to reduce the levels of pro-inflammatory cytokines including TNF-α, IL-1, or IL-6 often associated with certain psychiatric disorders." (PMID 36133749, 2022). "Elevated levels of pro-inflammatory cytokines such as interleukin-6 (IL-6) and tumor necrosis factor-alpha (TNF-α) are frequently observed in individuals with psychiatric disorders." (PMID 40141685, 2025). "Recent studies showed that blood biomarkers have been used to predict health status in individuals with psychiatric disorders and OB, including the interleukins (IL-6, IL-10), tumor necrosis factor alpha (TNF-α), and C-reactive protein (CRP)." (PMID 39752432, 2025). "A connection between inflammation and psychiatric disorders has been identified in the context of Calcium Channel Blockers (CCBs), which are suggested to elevate TNF-alpha (an inflammatory factor)." (PMID 39184138, 2024). "CRP and many serum cytokines levels have been recently suggested as biological biomarkers of psychiatric diseases and skin diseases such as TNF-α, IL-1β, IL-6, and IL-18." (PMID 39624485, 2024). "This CSF panel includes interleukin (IL)-1β, IL-6, IL-8, IL-10, C-reactive protein (CRP), and tumor necrosis factor-alpha (TNF-α); inflammatory cytokines that have been linked to neuropsychiatric symptoms occurring in neurological and psychiatric disorders." (PMID 38336728, 2024). "It has been suggested that dysregulation of cytokines, particularly IL-1-β, IL-6, IL-10, interferon (IFN-γ), and TNF-α, contributes to the pathogenesis of certain psychiatric disorders." (PMID 37644934, 2023). "In fact, it is clear from the literature that the increase in proinflammatory cytokines, such as IL-1, IL-6 and TNF-α, and imbalances in T cells are directly responsible for the development of psychiatric disorders." (PMID 36835652, 2023). "The authors found elevated levels of IL-4, IL-10, tumor necrosis factor (TNF)-α, and TNF-β in the amniotic fluid were associated with ASD, whereas elevated levels of IL-5 and IL-6 associated with other childhood psychiatric disorders." (PMID 33327930, 2020). "Blocking TNF-α not only reduced psychiatric disorders but also reduced chronic pain at the same time." (PMID 30208926, 2018). "For example, pro-inflammatory cytokines including TNF-α have been reported to be elevated in psychiatric disorder patients." (PMID 30072733, 2018). "TNF-α is another pro-inflammatory cytokine that plays a pivotal role in the development of psychiatric disorders." (PMID 30208926, 2018).
psychiatric disorder (continued). "In addition, the overactivated inflammatory processes (such as IL-1, IL-6, IL-15, and TNFα) that observed among both OA patients and patients with psychiatric disorders implied the possibility of shared biological pathways between these two traits." (PMID 40224608, 2023). "TNF-α may contribute to the pathogenesis of psychiatric disorders via hypothalamic-pituitary-adrenocortical axis activation, which leads to the immunologically mediated neurotoxic release of glutamate." (PMID 36835209, 2023). "High levels of pro-inflammatory cytokines, such as IL 6 and TNFα, were measured in the cerebral spinal fluid (CSF) of patients with psychiatric diseases and were correlated to microglia activity and the reduction of astrocyte and oligodendrocyte markers in brain parenchyma." (PMID 36676137, 2023). "TNF-α has been found to be of importance in many neurological and psychiatric disorders." (PMID 36061386, 2022). "The increase in oral bacteria load (Porphyromonas gingivalis, Streptococcus mutans, Treponema denticola, etc.), and the elevated concentrations of the inflammatory markers they induce (TNF α and cytokines), appear to be found in patients suffering from mental illness." (PMID 33260581, 2020). "The elevation of peripheral IL-1β, IL-6 and TNF-α could be a potential biomarker of vulnerability for psychiatric disorders in adults but their roles remain unknown for elderly." (PMID 30104698, 2018). "TNF-α was initially described as a cell death inducer, and as a proinflammatory cytokine, it is generally recognized as a worsening factor in the pathology of psychiatric disorders." (PMID 28373844, 2017). "This subsequently reduces the level of pro-inflammatory factors, such as the cytokines TNF-α and IL-1β, chemokines, TLRs, and CRP, helping in alleviating both systemic and neuroinflammation, the latter being the causal factor for most psychiatric disorders." (PMID 24772064, 2014). "TNF is a white cell produced pro-inflammatory cytokine likely involved in depressive disorder which has been poorly investigated as a mediator of alcohol related psychiatric disorders." (PMID 19742166, 2009). "Pro-inflammatory cytokines, such as tumor necrosis factor-alpha (TNF-α), interleukin-6 (IL-6), and interleukin-1β (IL-1β), are implicated in both the pathogenesis of IBD and the onset of psychiatric disorders, suggesting that systemic inflammation may underlie the comorbidity of these conditions." (PMID 40823034, 2025). "Additionally, shared etiologies were also a rational speculation, since overactivated inflammatory factors (such as IL-1, IL-6, IL-15, and TNFα) and altered immune response were observed among both OA and psychiatric disorders patients." (PMID 40224608, 2023). "In conclusion, TNF-α may lead to psychiatric disorders via an activation of a neuroendocrine system such as the HPA axis, the activation of neurotransmitter transporters such as the serotonin transporter, the influence on the metabolism of neurotransmitters and the autoimmune destruction of neurons." (PMID 19506720, 2008). "Furthermore, alterations in cytokine secretion, such as increased levels of the inflammatory markers interleukin-6, TNF-a, and C-reactive protein, which contribute to dysfunctional immune responses, is another possible mechanism by which exposure to psychiatric disorders may be related to CRC risk." (PMID 41530201, 2026). "Previous studies noted higher blood levels of inflammatory biomarkers (including IL-6, IL-1β, TNF-α, and CRP) in people with mental illness who have suicidal attempts in comparison to healthy controls or non-suicidal people with mental illness." (PMID 39882160, 2024). "Concordant results were obtained for adult psychiatric disorders where circulatory cytokine levels were significantly increased (IL1-RA, IL-18, TNF, IL-6, and C-Reactive Protein)." (PMID 36339838, 2022).